PDE4B (phosphodiesterase 4B)
Diseases named in the same sentence as PDE4B in open-access papers (continued):
Sharing a sentence is not in itself a finding about the gene and the disease.
colon cancer (6 papers, 2018 to 2025). "It has been reported that PDE4B overexpression is associated with promoting the pathogenesis of hematologic malignancies and some solid tumors, such as colon cancer and bladder cancer." (PMID 36737782, 2023). "Many of these mutant alleles of PDE4B occur in colonic cancers that also carry truncations of the canonical gatekeeper gene APC." (PMID 30188895, 2018). "Combining our studies with reports in the literature, we deduced that, by catabolizing cyclic AMP, the phosphodiesterase encoded by the gene of interest, Pde4b, protects against the early stages of colon cancer in the mouse." (PMID 30188895, 2018). "By array analysis, we observed that the Pde4b transcript level is enhanced in the normal colonic epithelium adjacent to colonic tumors in ApcMin/+ mice, compared to that of the normal colonic epithelium of tumor-free ApcMin/+ mice." (PMID 30188895, 2018). "In summary, we have combined mutational analysis in the ApcMin/+ mouse with published studies of frank colon cancer in patients to deduce that Pde4b has two strong biological functions." (PMID 30188895, 2018). "ApcMin/+ mice that are wildtype for Pde4b, have significantly elevated colonic tumor counts after treatment with DSS." (PMID 30188895, 2018). "These mutational and silencing observations in patients are consistent with PDE4B serving a protective function in the major APC-dependent pathway to frank colon cancer." (PMID 30188895, 2018). "Enhanced levels of the Pde4b transcript in the normal colonic epithelium adjacent to colonic tumors—A protective field effect?" (PMID 30188895, 2018). "PDE4B also restricts cAMP levels in colon cancer and abrogates cAMP-induced anticancer effect." (PMID 38233872, 2024). "However, in patients with advanced colon cancer, PDE4B may become inactivated through epigenetic suppression." (PMID 40129976, 2025). "Adenylate cyclase overexpression or PDE4B silencing may increase cAMP levels in colon cancer." (PMID 38233872, 2024). "Finally Pde4b-/- mice show the highest average colon tumor number 4.3 ± 4.6." (PMID 30188895, 2018). "PDE4B is specifically relevant to the issue of a sensitizing versus protective field effect in human colon cancer because it has been reported to be expressed in “non-neoplastic appearing colonic mucosa from patients with colorectal neoplasia”." (PMID 30188895, 2018).
ovarian carcinoma (6 papers, 2021 to 2024). A malignant neoplasm originating from the surface ovarian epithelium. "By demethylating m6A at the 3'UTR of phosphodiesterases PDE1C and PDE4B, FTO inhibits PDE1C and PDE4B expression and thereby enhances cAMP signaling, which suppresses ovarian cancer cells stemness." (PMID 38233872, 2024). "Overexpression of FTO led to hypomethylation and reduced mRNA stability of two phosphodiesterase genes (PDE1C and PDE4B) but augmented cAMP signaling and dampen stemness features of ovarian cancer cells." (PMID 38714753, 2024). "For example, PDE4B can act as a target that modulates cAMP signaling pathway and plays a key role in maintaining the stemness of ovarian cancer, while cAMP/PDE4B signaling pathway can also modulate the malignant phenotype of CRC cells." (PMID 36278172, 2022). "m6A can also regulate the stemness of ovarian cancer stem cells by stabilizing the mRNA of the phosphodiesterase, PDE1C, and PDE4B and stimulating the stemness of ovarian cancer cells through the cyclic adenosine monophosphate (cAMP) signaling pathway." (PMID 33898522, 2021). "Recently, studies have showed that FTO can constrain ovarian cancer stem cells by promoting the decay of PDE1C and PDE4B mRNA." (PMID 35397614, 2022). "However, in ovarian cancer, overexpression of FTO reduces m6A levels and mRNA transcript stability which inhibits the hydrolysis of the second messenger cAMP mediated by two phosphodiesterases, PDE1C (phosphodiesterases 1C) and PDE4B (phosphodiesterases 4B)." (PMID 38343637, 2024).
breast carcinoma (5 papers, 2016 to 2026). "POG570 tumors with SV breakpoints near PDE4B involved 22 patients, 16 of which had breast cancer and 15 of which were treated with anthracycline." (PMID 34788622, 2021). "We analyze in depth two regulatory variants—breast cancer risk SNP rs11055880 and leukemia risk-associated SNP rs12142375—and demonstrate their endogenous regulatory activities on expression of ATF7IP and PDE4B genes, respectively, using a CRISPR-Cas9 approach." (PMID 29061142, 2017). "Surprisingly, further analysis of established breast cancer cell lines using datasets from Cancer Cell Line Encyclopedia showed that PDE4A, rather than PDE4B was overexpressed in TNBC cell lines compared with ER+ ones." (PMID 27901486, 2016).
acute myocardial infarction (4 papers, 2023 to 2025). Necrosis of the myocardium, as a result of interruption of the blood supply to the area. "The development of subtype-selective PDE4B inhibitors or the repurposing of existing PDE drugs may become a new cardiac protective agent for patients with acute myocardial infarction during reperfusion." (PMID 40176832, 2025). "Similarly, targeting PDE4B in acute myocardial infarction may reduce infarct size and protect microvessels by regulating neutrophil inflammatory response." (PMID 39691395, 2024). "Meanwhile, the expression of PDE4B but no other PDE4 subtypes increases in mouse hearts with myocardial infarction-reperfusion (MI/R) injury." (PMID 37971403, 2024).
autism (4 papers, 2016 to 2022). Persistent deficits in social interaction and communication and interaction as well as a markedly restricted repertoire of activity and interest as well as repetitive patterns of behavior. "PDE4B has also been identified as one of the subset genes related to a common molecular signature in autism." (PMID 33362469, 2020). "Four genes in our candidate list for autism (MAP1LC3B, PDE4B, TCF4 and UPF2) have already been associated with ASD." (PMID 26731442, 2016). "Four of the Root 66 genes (MAP1LC3B, PDE4B, TCF4 and UPF2) have previously been associated with autism, and 56 either have been shown to interact directly with known autism candidates or have been implicated in other autism-related neurological disorders." (PMID 26731442, 2016). "The first network included 15 Root 66 genes, 2 of them already associated with autism (MAP1LC3B and PDE4B), that interact in neurological processes involved in normal brain growth and function, such as formation of astrocytes, proliferation of cortical neurons, sorting of axons and myelination." (PMID 26731442, 2016).
B-cell lymphoma (4 papers, 2016 to 2025). "Initial evidence implicating a connection between PDE4B and B-cell lymphoma emerged from comprehensive genomic profiling analyses." (PMID 40129976, 2025). "PDE4B, an isoform of PDE4, is highly expressed in refractory DLBCL patients and the anticancer effect of PDE4 inhibitors has been confirmed in B-cell lymphoma in vitro and in vivo, associated with repression of the SYK/AKT/mTOR pathway." (PMID 34833935, 2021). "This indicates that B-cell lymphomas might necessitate stratification into PDE4B-high and PDE4B-low expression groups to facilitate personalized combination therapies incorporating PDE4 inhibitors." (PMID 40129976, 2025). "Meanwhile, miR-124 also increases sensitivity of B-cell lymphomas to glucocorticoid treatment by targeting phosphodiesterase 4B (PDE4B) and may act as an attractive therapeutic target in B cell lymphoma." (PMID 27757114, 2016). "PDE4B was reported to be highly expressed in CD4+ lymphoid cancer cells, with a role in promoting angiogenesis in B-cell lymphoma." (PMID 29061142, 2017).
bladder cancer (4 papers, 2018 to 2023). "It has been shown that PDE4B in our prognostic model gene induces epithelial-mesenchymal transition in bladder cancer cells and is transcriptionally repressed by CBX7." (PMID 36579330, 2022).
brain injury (4 papers, 2020 to 2024). Acute and chronic (see also brain INJURIES, CHRONIC) injuries to the brain, including the cerebral hemispheres, CEREBELLUM, and brain STEM. "Inhibition of PDE4B with i.p. injections of 0.3 mg/kg A33 decreased neuronal loss in traumatic brain injury." (PMID 37175842, 2023). "Pharmacological inhibition of PDE4B by 0.3 ​mg/kg A33 i.p. administered 30 ​min after traumatic brain injury induction, induced anti-inflammatory markers (e.g., Arginase-1) in phagocytes and limited lesion size." (PMID 38760316, 2024). "In addition, TNF-α increases PDE4B expression and nuclear translocation in microglia and PDE4B is highly expressed in activated microglia after traumatic brain injury and spinal cord injury." (PMID 37525115, 2023). "PDE4B was revealed to be an especially crucial mediator for neutrophil infiltration in the CNS, since intraperitoneal (i.p.)administration of 3 mg/kg A33, 30 min and 5 h pi reduced neutrophil infiltration in traumatic brain injury." (PMID 37175842, 2023). "For example, this pathway is modulated in monocytes, macrophages and microglia by phosphodiesterase-4B (PDE4B), while treatment with a PDE4B allosteric inhibitor after acute brain injury reduces microglial activation, reduces production of TNF, and provides neuroprotective benefit in rats." (PMID 32203525, 2020).
gastric cancer (4 papers, 2023 to 2025). A primary or metastatic malignant neoplasm involving the stomach. "PDE4B also affects gastritis-associated gastric cancer, and targeted inhibition of PDE4B can be involved in inhibiting the process of inflammation-associated gastric cancer." (PMID 38414734, 2024). "PDE4B has emerged as a significant player in various aspects of cancer biology, particularly in the diagnosis, classification, treatment, and prognosis of different malignancies, including bladder cancer, gastric cancer, and prostate cancer, among others." (PMID 40564004, 2025). "Meanwhile, hsa-miR-26b-5p directly interacts with PDE4B and CDK8, thereby downregulating STAT3 phosphorylation and nuclear translocation, and promoting gastric cancer cell proliferation." (PMID 38796629, 2024).
heart failure (4 papers, 2021 to 2025). Inability of the heart to pump blood at an adequate rate to meet tissue metabolic requirements. "Altogether, decreases in PDE4D activity, which represents the main PDE4 isoform in human cardiac tissue, might favor idiopathic dilated cardiomyopathy and its deficiency in the RyR complex promotes heart failure and arrhythmias, whereas PDE4B prevents Ca2+ overload and arrhythmias." (PMID 36142518, 2022). "Cardiac PDE4B overexpression is beneficial in remodeling and heart failure (HF), however, the effect of PDE4D and PDE4 inhibitor in HF remains unclear." (PMID 40015131, 2025). "It should be noted that heart failure in rat induces increases in the PDE4B protein and mRNA expressions in the aorta which could contribute to high blood pressure." (PMID 36142518, 2022). "PDE4B is a protective cyclic AMP-phosphodiesterase involved in heart failure and colon cancer." (PMID 34294701, 2021). "This review highlights the cardiac PDE4 isoforms PDE4A, PDE4B and PDE4D, focusing on their distinct localisation and contributions to cardiac physiology and pathophysiology, particularly in heart failure and arrhythmias." (PMID 40136709, 2025).
Hypertension (4 papers, 2021 to 2025). The presence of chronic increased pressure in the systemic arterial system. "In this study, we identified phosphodiesterase 4B (PDE4B) as a key mediator in the development of OSA-related hypertension." (PMID 41243803, 2025). "Only three of the 23 unique genes replicated, have been directly associated with hypertension (GPER1, PDE4B and TNFAIP3) so far." (PMID 35446883, 2022). "Between carvedilol and timolol there was an overlap of 15 genes, causing an upregulation, among others, of GPER1, PDE4B and TNFAIP3, which are genes directly associated with hypertension." (PMID 35446883, 2022). "Our results also showed the reduced level of Pde4b in hypertension and the reversal effect of berberine on its expression." (PMID 33621262, 2021). "In the case of carvedilol, we showed that, beside genes with well-established association with hypertension (GPER1, PDE4B and TNFAIP3), the drug also affects genes that are only indirectly linked to hypertension due to their effects on artery walls or their role in lipid biosynthesis." (PMID 35446883, 2022).
lung carcinoma (4 papers, 2017 to 2022). "Similar to other tumors, PDE4B is also involved in the growth of lung cancer cells through cAMP, and cAMP acts as a second messenger that can regulate cellular responses through activated effectors." (PMID 36278172, 2022). "PDE4B expression was found to be increased in non-small cell lung cancer tissues, and additional study highlights in vitro findings that specific PDE4B inhibition is cytotoxic in lung cancer cells." (PMID 33585210, 2020). "Therefore the role of PDE4B in lung cancer cannot be ignored." (PMID 36278172, 2022). "Therefore, PDE4B is likely to be a regulator of the occurrence and development of lung cancer." (PMID 36278172, 2022). "Six genes showed particularly stronger expression pattern in lung cancer tissues, as compared to normal lungs, which demonstrated that these six genes (GABBR1, PDE4B, PDE4C, ADCY6, ADCY1 and GIPR) had more likelihood of being direct targets of miR-542-5p in lung cancers." (PMID 28927388, 2017).
Lymphoid Cancer (4 papers, 2013 to 2020). "Experiments with genetically or pharmacologically inhibited PDE4B resulted in decreased VEGF-A expression in lymphoma cells and reduced angiogenesis in the Eμ-Myc high-grade lymphoma mouse model." (PMID 33343570, 2020). "Moreover, PDE4B was found to be highly expressed in CD4+ lymphoid cancer cells, which suggests that it may represent a physiological role unique to the CD8+ and lymphoid cancer cells and thus might represent a target for pharmaceutical intervention for certain lymphoid diseases." (PMID 23451206, 2013).
melanoma (4 papers, 2022 to 2025). A malignant, usually aggressive tumor composed of atypical, neoplastic melanocytes. "The signature gene PDE4B, higher expressed in patients with more survival, was positive correlated with T cells in melanoma tumors." (PMID 39132169, 2024). "PDE4B promotes melanoma invasion and metastasis by inhibiting the cAMP signaling pathway." (PMID 36278172, 2022). "We also found the signature gene PDE4B, higher expressed in patients with more survival, was positive correlated with CD8+ T cells in melanoma tumors." (PMID 39132169, 2024). "Silencing PDE4B or PDE4D significantly reduced PDE4 activity in melanoma cells, whereas PDE4A had no such effect, suggesting that PDE4B and PDE4D play crucial roles in regulating PDE4 activity in melanoma." (PMID 40129976, 2025).
psoriasis (4 papers, 2022 to 2025). An autoimmune condition characterized by red, well-delineated plaques with silvery scales that are usually on the extensor surfaces and scalp. "The goal of this study was to utilise tape strip sampling to investigate changes in protein skin levels of psoriasis patients after oral treatment with orismilast (a PDE4B/D inhibitor)." (PMID 40970551, 2025). "Orismilast is a potent PDE4 inhibitor with high selectivity for the PDE4B and PDE4D subtypes and demonstrated significant efficacy versus placebo at Week 16 in patients with moderate‐to‐severe psoriasis, both for percentage change in PASI and proportions of patients achieving PASI75 and PASI90." (PMID 40970551, 2025). "Indeed, PDE4B and PDE4D were found to be overexpressed in PBMCs from patients with Psoriasis, an inflammatory disease characterized by the dysfunction of dermal fibroblasts." (PMID 37887031, 2023).
alcohol dependence (3 papers, 2022 to 2025). Physical and psychological dependence on alcohol. "Similarly, rs1937455 in PDE4B was associated with a lower risk of alcohol dependence, lower GGT levels and lower BMI." (PMID 38632349, 2024). "In contrast, PDE4B is highly expressed in the striatum, amygdala, and the bed nucleus of the stria terminalis, indicating that PDE4B may be a key player in alcohol dependence and abuse." (PMID 39921664, 2025). "Having confirmed the potential of KVA-D88 to inhibit PDE4B activity and suppress inflammation in vitro, we tested the efficacy of KVA-D88 loaded NPs in mice using the NIAAA model that is suitable for studying ALD pathogenesis and alcohol-related damage." (PMID 36145643, 2022).
allergic disease (3 papers, 2011 to 2022). An immune response that occurs following re-exposure to an innocuous antigen, and that requires the presence of existing antibodies against that antigen. "Other research reveals increased expression of PDE-4B and PDE-4D variants in the bronchiolar lavage fluid of treated animals with ovalbumin; however, inhibiting the PDE-4B subtype significantly cured rodent allergies." (PMID 35890197, 2022).
Cognitive impairment (3 papers, 2011 to 2025). Abnormal cognition is characterized by deficits in thinking, reasoning, or remembering. "In the present study, we demonstrated for the first time that the PDE4B inhibitor A33 prevented cognitive impairment and Aβ deposition in an animal model of AlD, primarily by alleviating neuroinflammatory reactions in the hippocampus via the activation of the PDE4B/cAMP/PKA signaling pathway." (PMID 39921664, 2025). "The recent large scale GWAS studies of human cognitive ability suggest the potential of PDE1C, PDE4B and PDE4D inhibitors to address cognitive impairment across multiple CNS disorders." (PMID 30800055, 2019).
colitis (3 papers, 2020 to 2023). Inflammation of the colon. "The results suggest that triptolide treatment to reduce DSS-induced colitis may be related to the inhibition of the PDE4B/AKT/P65 signal cascade." (PMID 33240279, 2020). "Our data suggested that triptolide treatment effectively inhibited DSS-induced colitis and that PDE4B may be a crucial regulatory molecule of triptolide." (PMID 33240279, 2020). "The results showed that PDE4B was significantly upregulated in DSS-induced colitis tissue." (PMID 33240279, 2020). "Interestingly, PDE4B was clearly inhibited by triptolide administration in both DSS-induced colitis and LPS-activated macrophages." (PMID 33240279, 2020).
inflammatory bowel disease (3 papers, 2018 to 2024). A spectrum of small and large bowel inflammatory diseases of unknown etiology. "Because high levels of PDE4B are present in UC patients, we provide the basis for a greater understanding of inflammatory signaling in UC, suggesting that miR-369-3p, by ameliorating inflammatory conditions, could be used as a new therapeutic approach to inflammatory bowel disease." (PMID 39126032, 2024). "Sets of mice with each Pde4b and Apc genotype were then divided into two groups, one treated with Dextran Sodium Sulfate (DSS), a model of inflammatory bowel disease (IBD), and the other left untreated." (PMID 30188895, 2018).
liver fibrosis (3 papers, 2021 to 2025). "Recent findings have highlighted a previously unrecognized anti-fibrotic pathway where Smurf2 interacts with PDE4B, leading to the degradation of PDE4B and attenuation of liver fibrosis." (PMID 40564004, 2025).